MIR4447 (microRNA 4447)
Synonyms: hsa-mir-4447
Gene: MicroRNA gene on chromosome 3 (116,850,277 to 116,850,367, reverse strand). Ensembl gene ENSG00000265433.
Homologues: Orthologues: chimpanzee MIR4447 (100% identical).
Diseases named in the same sentence as MIR4447 in open-access papers:
MIR4447 is named in the same sentence as 3 diseases in open-access papers, as found by Europe PMC text mining. Sharing a sentence is not in itself a finding about the gene and the disease. The quoted sentences say what the papers report.
lymphoma (1 paper, 2019). A malignant (clonal) proliferation of B- lymphocytes or T- lymphocytes which involves the lymph nodes, bone marrow and/or extranodal sites. "The RNU5E-8P (3q13.31), MIR4447 (3q13.31), RP11–351J23.2 (6q27), and LINC00939 (12q24.32), have to the best of our knowledge not yet been associated with cancer, though RP11–351J23.2 is located in a candidate tumor suppressor gene locus in lymphomas identified by deletion mapping." (PMID 30926794, 2019).
MIR4447 also shares sentences with these, for which no sentence is quoted: cancer (1 paper); tumor (1).